MTOR (mechanistic target of rapamycin kinase)
Diseases named in the same sentence as MTOR in open-access papers (continued):
Sharing a sentence is not in itself a finding about the gene and the disease.
atherosclerosis (continued). "The KEGG analysis results showed that the therapeutic approaches of HSHP against atherosclerosis were mainly related to hemodynamic, metabolic disorders, and inflammatory signalling pathways, including fluid shear force and IR, as well as AMPK, cAMP, and mTOR signalling pathways." (PMID 34887932, 2021). "Thus, regardless of dyslipidemia profile, mTOR inhibitors appear to result in a net reduction in the rate of atherosclerosis, which may explain the overall clinical benefit observed." (PMID 36211586, 2022).
lung adenocarcinoma (180 papers, 2009 to 2026). A carcinoma that arises from the lung and is characterized by the presence of malignant glandular epithelial cells. "In some cases, high p-mTOR levels were associated with low p-S6 and high Rictor expression, which characterized about 20% of primary lung adenocarcinomas and more than 50% of brain metastases." (PMID 38515456, 2024). "For example, HKDC1 has been implicated in tumorigenesis of lung adenocarcinoma through modulation of AMPK/mTOR signaling." (PMID 37082446, 2023). "MMP1 has been already reported to cause resistance of lung adenocarcinoma to EGFR-TKIs through mTOR pathways." (PMID 35480306, 2022). "Evidence has demonstrated that the mammalian target of rapamycin (mTOR) signaling pathway was associated with metastasis and cisplatin resistance in lung adenocarcinoma." (PMID 32596372, 2020). "Phosphorylation mediated by PI3K and mTOR is implicated in glucose uptake by brown fat cells and lung adenocarcinoma cells." (PMID 31748639, 2019). "Smoking is reported to activate mTOR pathways, and there is a significant correlation between mucinous-type lung adenocarcinoma and k-ras mutation, and between smoking and k-ras mutation." (PMID 29463039, 2018). "mTOR was associated with drug resistance in lung adenocarcinoma after radiation combined with TKI, and MTOR inhibition reversed drug resistance in lung adenocarcinoma after combined radiation and TKI therapy." (PMID 27713162, 2016). "Aberrant activation of the PI3K/AKT/mTOR pathway is one of the mechanisms of acquired resistance to EGFR-TKI in patients with lung adenocarcinoma carrying EGFR activating mutations." (PMID 25978653, 2015). "AC084757.3 is implicated in lung adenocarcinoma via PI3K/Akt/mTOR pathway." (PMID 40281132, 2025). "To conclude, this study is the first to reveal that MMP-1 plays an important role in the migration and invasion abilities of EGFR-TKI–resistant lung adenocarcinoma cells, and the mTOR pathway is associated with the induction of MMP-1 expression in these cells, resulting in a poor prognosis." (PMID 29463039, 2018). "Additionally, the mTOR pathway is associated with induction of MMP-1 expression in lung adenocarcinoma, including EGFR-TKI–resistant cells." (PMID 29463039, 2018). "mTOR pathway may be activated in lung adenocarcinomas through three different molecular mechanisms: PI3KCA mutations, STK11 mutation associated or not with low levels of LKB1." (PMID 30060526, 2018). "To elucidate how EGFR signaling is linked to metabolic activity, we investigated the involvement of the RAS/MEK/ERK and PI3K/AKT/mammalian target of rapamycin (mTOR) pathways on metabolic alteration in lung adenocarcinoma (LAD) cell lines with activating EGFR mutations." (PMID 26023239, 2015). "ModSDP identified the mTOR signaling pathway in lung squamous cell carcinoma and the FoxO signaling in lung adenocarcinoma, which can help with understanding subtype heterogeneity." (PMID 40768543, 2025). "Up-regulation of SELENBP1 expression inhibits the activation of PI3K/AKT/mTOR signaling pathway, thereby hindering the malignant development of lung adenocarcinoma." (PMID 40732347, 2025). "Subtype comparisons highlight the mTOR signaling in lung adenocarcinoma and the FoxO signaling in lung squamous cell carcinoma." (PMID 40768543, 2025). "For instance, a study showed that HKDC1 promotes tumorigenesis and glycolytic metabolism in lung adenocarcinoma by regulating the AMPK/mTOR signaling pathway, suggesting a direct link between HKDC1 expression and metabolic reprogramming of cancer cells." (PMID 41049000, 2025). "The pan-cancer analysis of the TCGA database revealed a positive correlation between ELK1 expression and the expression of MTOR in most cancer types, including lung adenocarcinoma and lung squamous carcinoma." (PMID 38397056, 2024). "MiR-206 reduced EMT process and CDDP resistance via MET targeting that inhibited PI3K/AKT/mTOR axis in lung adenocarcinoma cells." (PMID 38730433, 2024).
lung adenocarcinoma (continued). "Oncogenic zinc finger protein ZNF687 activates PI3K/Akt/mTOR signaling pathway to accelerate lung adenocarcinoma cell proliferation and tumor progression." (PMID 39717098, 2024). "In our studies, we examined the p-mTOR, p-S6, and Rictor proteins in situ in primary lung adenocarcinomas and brain metastases." (PMID 38515456, 2024). "miR-29c-3p suppresses the activity of Mitochondrial fission regulator 1 (MTFR1), thereby inhibiting the progression of lung adenocarcinoma via the AMPK/mTOR signaling pathway." (PMID 39712244, 2024). "For instance, EGF-like domain multiple 6 secreted by lung adenocarcinoma cells can enhance the EMT process, activate the Wnt/β-catenin and PI3K/AKT/mTOR pathways, promoting lung adenocarcinoma cell proliferation, migration, and invasion capabilities." (PMID 38571500, 2024). "For instance, FABP5 has been reported to promote tumor progression by mediating fatty acid metabolism and stabilizing PI3K/AKT/mTOR signaling in lung adenocarcinoma." (PMID 36792587, 2023). "Ror is also reported to activate the PI3K/Akt/mTor signaling pathway in lung adenocarcinoma or multiple myeloma." (PMID 36647607, 2023). "Antrodin C potently inhibited the viability of human lung adenocarcinoma cell lines, induced apoptosis triggered by ROS, and arrested the cell cycle at the G2/M phase by suppressing both the Akt/mTOR and AMPK signaling pathways." (PMID 36979011, 2023). "The first patient (Patient 33) is a 63-year-old Chinese male who was diagnosed with lung adenocarcinoma accompanied by mediastinal lymph node metastasis and double lung metastasis with a rare PRDX1-NTRK1 fusion and an MTOR E2419D mutation." (PMID 37567953, 2023). "The silencing of ROR1 significantly inhibited the proliferation of tumor cells in lung adenocarcinoma via the PI3K/AKT/mTOR signaling pathway." (PMID 37111634, 2023). "Our study provides insight into how exosomes promote invasion and hybrid EMT in EGFR-mutated lung adenocarcinoma, most likely through the PI3K/AKT/mTOR pathway." (PMID 35954442, 2022). "Kaplan–Meier curve revealed that mTOR high mRNA levels correlate with poorer prognostic and survival, suggesting proactive involvement of this gene in the malignancy in lung adenocarcinoma." (PMID 35887120, 2022). "In this study, we demonstrated that the downregulation of YAP induced autophagy and then inhibited proliferation through PTEN/AKT/mTOR pathway in lung adenocarcinoma." (PMID 33413409, 2021). "We further clarified YAP manipulated proliferation through PTEN/AKT/mTOR-mediated autophagy in lung adenocarcinomas by enrichment analysis and mechanism research in vitro and in vivo." (PMID 33413409, 2021). "It was reported that the activation of the PI3K/Akt/mTOR pathway increased Slug expression in lung adenocarcinoma cells." (PMID 33573293, 2021). "Taken together, these findings demonstrated that the activity of mTOR was influenced by the expression of YAP via PTEN in lung adenocarcinoma." (PMID 33413409, 2021). "For example, miR-33a-5p has been found to promote lung adenocarcinoma chemosensitivity to celastrol owing to its ability to regulate the activity of mTOR." (PMID 32435616, 2020). "Downregulation of miR-33a-5p is beneficial for the chemo-resistance of lung adenocarcinoma cells via enhancing mechanistic target of rapamycin kinase (mTOR) signaling activation." (PMID 32505219, 2020). "In conclusion, the present study identified that ROR1 is a potential target for preventing erlotinib resistance in lung adenocarcinomas via the AKT/mTOR signaling pathway." (PMID 31452776, 2019).
lung adenocarcinoma (continued). "PCNP overexpression enhanced autophagy by increasing the expression levels of p-phosphatidylinositol 3-kinase (PI3K), p-Akt, and p-mammalian target of rapamycin (mTOR) in lung adenocarcinoma cells, however an opposite trend was observed in the sh-PCNP group." (PMID 30872582, 2019). "From these investigations, we present evidence that ViceninII prominently antagonizes TGF-β1-induced EMT by inactivating TGF-β/Smad and PI3K/Akt/mTOR pathways in lung adenocarcinoma A549 and H1299 cells." (PMID 30609689, 2019). "For the first time, we demonstrate that ViceninII targets the TGF-β/Smad and PI3K/Akt/mTOR pathways to inhibit TGF-β1-induced EMT phenotypes in lung adenocarcinoma A549 and H1299 cells." (PMID 30609689, 2019). "The results suggest that PCNP modulates autophagy via PI3K/Akt/mTOR signaling pathway in human lung adenocarcinoma cells." (PMID 30872582, 2019). "In the presence of mTOR activation, TKI-resistant lung adenocarcinoma cells showed a better response to combinational treatment with mTOR and TKIs." (PMID 31801598, 2019). "In this study, using a network-based cellular signature bioinformatics approach, we repurposed a clinically approved mTOR inhibitor for renal cell carcinomans, temsirolimus, as the potential therapeutic candidate for lung adenocarcinoma." (PMID 30087612, 2018). "To conclude, this study provides insights into the development of a possible alternative therapy manipulating MMP-1 and the mTOR signaling pathway in EGFR-TKI–resistant lung adenocarcinoma." (PMID 29463039, 2018). "These experiment results suggest that the autophagy in afatinib-treated lung adenocarcinoma cells is related to Akt/mTOR and Erk signaling pathway." (PMID 28676644, 2017). "The mechanism responsible for its tumor cell growth inhibitory activity involves the induction of autophagic cell death by suppressing Akt/mTOR signaling as recently reported in lung adenocarcinoma cell lines." (PMID 26769851, 2016). "Of note, Liza C. et.al reported a lung adenocarcinoma patient with FBXW7 deficiency both clinically and radiographically benefited from treatment with the mTOR inhibitor." (PMID 25749036, 2015). "An mTOR inhibitor had been used to treat his lung adenocarcinoma, but he developed aspiration pneumonia and died of respiratory failure." (PMID 26376867, 2015). "Everolimus, an mTOR inhibitor, was used for 10 days to treat the lung adenocarcinoma but was stopped after aspiration pneumonia began to develop." (PMID 26376867, 2015). "We identified several targetable pathways in EGFR/KRAS/ALK-negative lung adenocarcinoma including PI3K/mTOR signaling (TSC1, PIK3CA, AKT2), receptor tyrosine kinase signaling (ERBB4), cell cycle regulation (CHEK2, CDC27), and DNA repair (PARP4)." (PMID 24576404, 2014). "For in vitro experiments, NCI-H358, a human lung adenocarcinoma cell line, was co-cultured with immortalized astrocytes, and treated with rapamycin, an mTOR inhibitor." (PMID 23426399, 2013). "mTOR was recently demonstrated to regulate the expression of miR-143 in lung adenocarcinoma cell lines." (PMID 23420667, 2013). "We then examined two targets of Akt, mTOR and the S6 ribosomal protein, in lung adenocarcinoma cells." (PMID 23671619, 2013). "Thus, lung adenocarcinomas with loss or inactivation of STK11 have low AMPK activation and high mTOR activity." (PMID 40069402, 2025). "MiR-485 inhibited AKT and mTOR in lung adenocarcinoma that was reversed by FLOT2." (PMID 38730433, 2024).
lung adenocarcinoma (continued). "To demonstrate the use of pREF conu genes in an RNA sequencing experiment, we performed a drug-treatment experiment that evaluated the impact of torkinib treatment, a selective and ATP-competitive mTOR inhibitor, on gene expression in lung adenocarcinoma A549 cells." (PMID 38509097, 2024). "In the future, the combination of FBXO32 inhibitors with PI3K/AKT/mTOR inhibitor may be a potential way to reduce drug resistance and toxicity in lung adenocarcinoma." (PMID 38643215, 2024). "mTORC1 is hyperactive in LKB1/KRAS mutant lung adenocarcinoma cancer cells and, thus, targeting this pathway by mTOR inhibitors might represent an effective way of treating lung adenocarcinoma." (PMID 37190124, 2023). "For instance, almost 70% of breast and ovarian cancers carry an alteration of PI3K/AKT; similarly, the aberrant activation of the PI3K/AKT/mTOR pathway has been identified in 90% of lung adenocarcinomas (ADCs) and 40% of squamous cell carcinomas (SCCs), leading to its hyperactivation." (PMID 36765661, 2023). "It is interesting to note that the lncRNA MIR99AHG could promote autophagy by binding to ANXA2, then generate miR-99a to suppress the expression of mTOR, postponing lung adenocarcinoma progression." (PMID 35158722, 2022). "Notably, GTF2E2 was identified as the transcription factor that regulates the most genes which has been reported to exert inhibitory effects on lung adenocarcinoma in the mTOR pathway." (PMID 35749386, 2022). "Another research proved that miR-496 could regulate mTOR expression by directly binding to LnvRNA-DANCR in lung adenocarcinoma." (PMID 34818353, 2021). "Upregulation of the mTOR pathway is observed in up to 90% of lung adenocarcinoma patients." (PMID 34488540, 2021). "However, the expression levels of LC3 and mTOR in the metastatic bone tissues were higher than primary lung adenocarcinoma tissues." (PMID 34718338, 2021). "Additionally, neferine enhances cisplatin-induced autophagic cell death in human lung adenocarcinoma via downregulation of the PI3K/AKT/mTOR signaling pathway." (PMID 34575981, 2021). "For example, miR-33a-5p was found to be underexpressed in lung adenocarcinoma, which could directly target the mTOR pathway in vitro or in vivo to increase sensitivity to Celastrol, and improve antitumor effects and inhibit cell proliferation capacity." (PMID 34426559, 2021). "LncRNA DANCR facilitates lung adenocarcinoma progression by regulating miR-496/mTOR pathway." (PMID 32982585, 2020). "Then, we investigated whether a mTOR signaling inhibitor (BEZ235) could influence EGFR-TKI sensitivity in lung adenocarcinoma cells." (PMID 31801598, 2019). "The PI3K-AKT-mTOR pathway is an important pathway underlying drug resistance induced by combined radiation and TKI therapy, and inhibiting mTOR can reverse this drug resistance in lung adenocarcinoma." (PMID 27713162, 2016). "Furthermore, changes in in vitro survival curves, and in vivo growth curves before and after mTOR inhibition were evaluated to confirm its effects on drug resistance in lung adenocarcinoma after combined radiation and TKI therapy." (PMID 27713162, 2016). "Based on our results we speculate that the PI3K/AKT/mTOR signaling pathway could be one of the ways that ROR1-mediated survival signaling occurs in lung adenocarcinoma." (PMID 25978653, 2015).